ZBTB35 (zinc finger and BTB domain containing 35)
Description:
Plays a role during development and organogenesis as well as in the function of the adult central nervous system (By similarity). May be involved in transcriptional regulation as a repressor of ESR1/ER-alpha signaling.
Synonyms: ZNF131; pHZ-10
Tractability: PROTAC: UniProt records ubiquitination sites on it; ubiquitination databases record sites on it; its protein half-life has been measured.
Target class: Transcription factor
Gene: Protein-coding gene on chromosome 5 (43,065,176 to 43,192,021, forward strand). Ensembl gene ENSG00000172262.
Subcellular location: Nucleus
Subcellular location (Human Protein Atlas): Nucleoplasm; Intermediate filaments
Pathways (Reactome):
Metabolism of proteins: SUMOylation of transcription cofactors
Gene Ontology:
Molecular function: protein binding; DNA-binding transcription repressor activity, RNA polymerase II-specific; RNA polymerase II cis-regulatory region sequence-specific DNA binding; DNA-binding transcription activator activity, RNA polymerase II-specific; sequence-specific DNA binding
Biological process: B cell differentiation; negative regulation of transcription by RNA polymerase II; regulation of cytokine production; regulation of immune system process; T cell differentiation; positive regulation of transcription by RNA polymerase II
Cellular component: intermediate filament cytoskeleton; nucleoplasm; nucleus
Genetic constraint (gnomAD): Loss-of-function variants: 6 observed, 62.42 expected, observed/expected ratio (o/e) 0.0961, 90% interval 0.052 to 0.19. The upper end of that interval is the gene's LOEUF score, 0.19, which puts it in group 1 of 6, group 1 being the genes least tolerant of losing a copy. Missense variants: 492 observed, 768.79 expected, observed/expected ratio (o/e) 0.64, 90% interval 0.59 to 0.69. Synonymous variants: 256 observed, 267.13 expected, observed/expected ratio (o/e) 0.96, 90% interval 0.87 to 1.06.
Homologues: Orthologues: chimpanzee ZNF131 (99% identical), macaque ZNF131 (99% identical), dog ZNF131 (96% identical), rabbit ZNF131 (96% identical), guinea pig ZNF131 (95% identical), mouse Zfp131 (94% identical), rat Zfp131 (92% identical), pig ZNF131 (91% identical), tropical clawed frog ZNF131 (65% identical), zebrafish znf131 (49% identical), Drosophila melanogaster hb (11% identical), Drosophila melanogaster CG12391 (11% identical), and 2 more. Paralogues in human: PEG3 (14% identical), ZKSCAN2 (13% identical), ZSCAN29 (13% identical), REST (12% identical), ZNF274 (12% identical), ZNF770 (12% identical), ZSCAN32 (12% identical), ZNF518A (12% identical), ZNF202 (11% identical), ZNF18 (11% identical), ZNF496 (10% identical), ZNF174 (10% identical), and 17 more.
Diseases named in the same sentence as ZBTB35 in open-access papers:
ZBTB35 is named in the same sentence as 19 diseases in open-access papers, as found by Europe PMC text mining. Sharing a sentence is not in itself a finding about the gene and the disease.
ZBTB35 shares sentences with these, for which no sentence is quoted: tumor (3 papers); breast carcinoma (2); cancer (2); glioblastoma (2); lung carcinoma (2); adenocarcinoma (1); Alzheimer disease (1); bovine tuberculosis (1); brain tumors (1); Down syndrome (1); glioma (1); infection (1); Intellectual disability (1); Joubert syndrome (1); lung adenocarcinoma (1); lymph node metastasis (1); melanoma (1); Obesity (1); squamous cell carcinoma (1).